RGPD2 (RANBP2 like and GRIP domain containing 2)
Synonyms: RanBP2-like 2; RanBP2L2; RGP2; NUP358
Tractability: PROTAC: ubiquitination databases record sites on it.
Gene: Protein-coding gene on chromosome 2 (87,755,960 to 87,825,817, reverse strand). Ensembl gene ENSG00000185304.
Subcellular location (Human Protein Atlas): Nuclear membrane; Vesicles
Gene Ontology:
Molecular function: SUMO transferase activity
Biological process: NLS-bearing protein import into nucleus; nuclear export
Cellular component: nuclear pore; Golgi apparatus
Genetic constraint (gnomAD): Loss-of-function variants: 2 observed, 8.37 expected, observed/expected ratio (o/e) 0.24, 90% interval 0.097 to 0.75. That is too few expected variants to judge how well the gene tolerates losing a copy. Missense variants: 34 observed, 94.72 expected, observed/expected ratio (o/e) 0.36, 90% interval 0.27 to 0.48. Synonymous variants: 16 observed, 36.19 expected, observed/expected ratio (o/e) 0.44, 90% interval 0.3 to 0.67.
Homologues: Orthologues: zebrafish ranbp3a (5% identical), Drosophila melanogaster RanBP3 (5% identical). Paralogues in human: RGPD1 (99% identical), RGPD4 (95% identical), RGPD3 (95% identical), RGPD5 (93% identical), RGPD6 (93% identical), RGPD8 (93% identical), RANBP2 (83% identical), RANBP3 (7% identical), RANBP3L (4% identical), RANBP1 (4% identical).
Diseases named in the same sentence as RGPD2 in open-access papers:
RGPD2 is named in the same sentence as 6 diseases in open-access papers, as found by Europe PMC text mining. Sharing a sentence is not in itself a finding about the gene and the disease. The quoted sentences say what the papers report.
endometriosis (1 paper, 2024). The growth of functional endometrial tissue in anatomic sites outside the uterine body. "Among these genes, three (RGPD2, LTB, and KLRC1) exhibited distinct expression profiles between control and endometriosis-derived PBMCs." (PMID 39684780, 2024). "In the high JUP group, we identified several downregulated genes in the PBMCs from endometriosis patients, including HBB, HBA1, HBA2, RGPD2, CH25H, LTB, IFIT2 and JUN." (PMID 39684780, 2024). "Comparison between participants without endometriosis (n = 5) and participants with endometriosis (n = 4) with high serum JUP values (>220 ng/mL) identified nine DEGs (HBB, HBA1, HBA2, and RGPD2 in CD14+ monocytes; CH25H, HBB, LTB, and KLRC1 in γδt; IFIT2 in NK-CD56bright and JUN in Treg)." (PMID 39684780, 2024).
cancer (2 papers, 2022 to 2025). A tumor composed of atypical neoplastic, often pleomorphic cells that invade other tissues. "Upregulation of RGPD6, RGPD5, RGPD8, RGPD2, NUP210L, and PLCL1 has been observed in invasive tumors, implicating this functional network in the remodeling of ECM stiffness and integrin signaling, both of which enhance cancer cell migration." (PMID 40370715, 2025).
infection (1 paper, 2024). The state of being infected such as from the introduction of a foreign agent such as serum, vaccine, antigenic substance or organism. "On the other hand, six targets produced positive Z-scores (>1.96) that indicated increased infection upon CRISPR targeting: RANBP2-like and GRIP domain containing 2 and 4 (RGPD2 and RGPD4), trinucleotide repeat containing adaptor 6B (TNRC6B), FAM21C, KIA00196 (aka, strumpellin), and zyxin." (PMID 38953638, 2024).
tumor (1 paper, 2021). "The human RGPD2 gene is also known as the RANBP2-like GRIP domain containing 2, which shares a high degree of sequence identity with mouse RANBP2, a sizeable nuclear pore protein that has been described to act as a tumor suppressor for its role in preventing chromosome segregation errors." (PMID 34113558, 2021).
RGPD2 also shares sentences with these, for which no sentence is quoted: colitis (1 paper); diabetes (1).